APOE (apolipoprotein E)
Diseases named in the same sentence as APOE in open-access papers (continued):
Sharing a sentence is not in itself a finding about the gene and the disease.
vascular dementia (continued). "In summary, our study showed that habitual glucosamine use was significantly associated with a lower risk of incident vascular dementia in the older population, regardless of APOE genotypes and cognitive function." (PMID 37689747, 2023). "Interestingly, APOE ε4 has also been associated with increased risk for Lewy Body disease, including DLB and PDD, as well as with vascular dementia." (PMID 34679423, 2021). "The enrichment of nuclear receptor signaling (APOE and MMP9) links lipid metabolism, inflammation, and endothelial function, confirming the multidimensional nature of the etiology of vascular dementia." (PMID 41032496, 2025). "Therefore, targeted proteins, such as ApoE and APP, play significant roles in the progression of vascular dementia, highlighting potential therapeutic targets for intervention." (PMID 41032496, 2025). "The chosen proteins Apolipoprotein E (APOE), Amyloid Beta Precursor-Like Protein (APLP), Claudin-5 (CLDN5), Superoxide Dismutase (SOD), Matrix Metalloproteinase-9 (MMP-9), and Methylenetetrahydrofolate Reductase (MTHFR) play a key role in the progression of vascular dementia." (PMID 41032496, 2025).
aortic atherosclerosis (87 papers, 2007 to 2026). A atherosclerosis that involves the aorta. "Inhibition of circulating fatty acid synthase with platensimycin reduces foam cell formation in vitro and decreases aortic atherosclerosis in ApoE-deficient mice, highlighting its potential as a therapeutic target." (PMID 39972116, 2025). "Recently, it has been demonstrated that the main periodontal pathogens Porphyromonas gingivalis and Treponema denticola are causally associated with accelerated aortic atherosclerosis in ApoE-null hyperlipidemic mice." (PMID 40002744, 2025). "Independent of kidney injury, we found that loss of TPST1 and TPST2 decreased aortic atherosclerosis in ApoE−/− mice." (PMID 37424015, 2023). "Six-week-old ApoE deficient mice were fed with a high-fat Western diet (WD) for 6 weeks to induce aortic atherosclerosis." (PMID 36761778, 2023). "APOE gene deficiency disrupts lipid transport into the liver, resulting in the development of hyperlipidemia and the progression of aortic atherosclerosis." (PMID 33782520, 2021). "In aortic atherosclerosis-prone regions of the ApoE-deficient (ApoE-KO) mice, the expression of LOX as well as several genes encoding for ECM components, such as collagen I and fibronectin, were increased." (PMID 31615160, 2019). "Medline, Pubmed, Science direct and Web of Science were searched to identify studies which examined the effect of isolated flavonoids on aortic atherosclerosis in apolipoprotein E deficient mice." (PMID 28742839, 2017). "Irisin treatment (0.5 μg/g body weight/day) significantly reduced the severity of aortic atherosclerosis in apolipoprotein E-deficient mice fed on a high-cholesterol diet and suppressed carotid neointima formation in a carotid partial ligation model." (PMID 27355581, 2016). "TLR4 is known as the receptor of LPS, and its deficiency significantly attenuated aortic atherosclerosis in ApoE-/- mice." (PMID 24502419, 2014). "Both (-) and (+)-naloxone have also been found to be capable of reducing the severity of aortic atherosclerosis in apolipoprotein-E (apo-E)-deficient mice through inhibition of macrophage activation and superoxide release." (PMID 22340895, 2012). "Interestingly, selective overexpression of mutated human APP in the brain accelerated aortic atherosclerosis in ApoE-deficient mice." (PMID 32987857, 2020). "Additionally, APOE gene deficiency might be essential to development of hyperlipidemia and the progression of aortic atherosclerosis via aberrant hepatic lipid metabolism." (PMID 36428375, 2022). "ApoE KO rabbits exhibited a significant increase in aortic atherosclerosis when compared to WT controls." (PMID 39087075, 2024). "ORO and H&E staining were performed to evaluate the severity of aortic atherosclerosis in ApoE-/- mice fed with HFD." (PMID 37903785, 2023). "Feeding female A2Kb-Tg ApoE–/– mice with a high-cholesterol diet for 8 weeks starting at 9 weeks of age increased aortic atherosclerosis compared with normal chow feeding (17wk HC and 17wk NC, respectively)." (PMID 35536648, 2022). "PDZK1/ApoE DKO mice developed greater diet-induced aortic atherosclerosis compared with control ApoE knockout mice when fed a high-fat, Western-induced atherosclerotic diet." (PMID 36052278, 2022). "In summary, we firstly identified that the circulating and aortic levels of chemerin increased in the progression of aortic atherosclerosis in ApoE−/− mice." (PMID 31781638, 2019). "Further, ACAT-2–/– /ApoE–/– mice also had lower level of aortic atherosclerosis compared with controls." (PMID 30696703, 2019). "The present meta-analysis revealed that terpenoid administration is effective for attenuating aortic atherosclerosis in ApoE-/- mice." (PMID 31392210, 2019). "The main finding of this meta-analysis was that aortic atherosclerosis lesion area was significantly lower after administration of flavonoids compared with controls in ApoE-/- mice." (PMID 28742839, 2017).
aortic atherosclerosis (continued). "The aim of this systematic review and meta-analysis was to examine the effect of purified flavonoids on the severity of aortic atherosclerosis in ApoE-/- mice." (PMID 28742839, 2017). "Aortic atherosclerosis was induced in streptozotocin induced diabetic ApoE−/− mice by feeding with high-fat diet, and dapagliflozin was administrated intragastrically for 12 weeks as treatment." (PMID 28104929, 2016). "The ApoE−/− mice presented significantly larger areas of aortic atherosclerosis than C57 mice (29.5 ± 6.67% vs. 1.7 ± 0.61%, P = 0.002)." (PMID 26877097, 2016). "Our previous study showed that elevated TLR4 expression and activated NF-κB activity were observed in aortic atherosclerosis lesions of CUMS apoE-/- mice." (PMID 25860573, 2015). "Our results showed that miR-590 significantly inhibited the development of aortic atherosclerosis in apoE−/− mice fed high fat/high cholesterol Western diet." (PMID 26397958, 2015). "It should also be mentioned that collar-induced carotid atherosclerosis is different from natural aortic atherosclerosis in the ApoE−/− mice." (PMID 24729664, 2014). "Diabetic ApoE/GPx1 DKO mice show significantly more aortic atherosclerosis associated with enhanced macrophage recruitment, RAGE, and VCAM-1 expression compared to the diabetic ApoE KO mice." (PMID 23761786, 2013). "Expression of apoE in BM-derived cells has previously been shown to protect against aortic atherosclerosis in apoE KO mice." (PMID 23967310, 2013). "Assessment of atherosclerotic lesions after feeding mice a HFD by oil red-O stained lipid accumulation showed that BaffR.ApoE DKO mice had a significant ∼44% reduction in aortic atherosclerosis compared to ApoE KO mice (p<0.01)." (PMID 22238605, 2012). "In this study we show that immunization of apoE (-/-) mice with p210, a 20 amino acid apoB-100 related peptide, reduced aortic atherosclerosis compared with PBS or adjuvant/carrier controls." (PMID 22347402, 2012). "The effects of inhaled PM2.5 on aortic atherosclerosis have been assessed on apoE null mice subject to long-term exposures to concentrated ambient particles (CAPs) performed at the A.J. Lanza Exposure Laboratory of New York University in Tuxedo, NY." (PMID 19761620, 2009). "Our findings furnish a new mechanism through which pravastatin can prevent aortic atherosclerosis via attenuating IL-6 action by the modulation of STAT3 activity in apoE-/- mice." (PMID 19330073, 2008). "To determine whether the expression of HSPs also ameliorates aortic atherosclerosis after the formation of atheromas, we induced the expression of HSPs in ApoE−/− mice after with formed atheromas." (PMID 33782520, 2021). "Thus, the results suggested inherently differential profiles of immune regulation between female and male apoE–/– mice even as aortic atherosclerosis was comparable." (PMID 32373127, 2020). "In the present study, we investigated the time course of ETAR expression in high-fat diet-induced aortic atherosclerosis in ApoE−/− mice and in human advanced atherosclerotic plaques in correlation to smooth muscle actin (SMA) and matrix metalloproteinase 9 (MMP-9)." (PMID 33255872, 2020). "The aims of the present study were to explore the effects of dapagliflozin on aortic atherosclerosis in diabetic versus nondiabetic ApoE−/− mice and detect the possible underlying mechanism, particularly their influence on the ROS-NLRP3-caspase-1 pathway." (PMID 28104929, 2016). "ApoE-deficient mice are the mouse model most often used to investigate aortic atherosclerosis, but they do not show coronary occlusion." (PMID 23950999, 2013). "Therefore, we first evaluated the effects of berberine on the severity of aortic atherosclerosis in ApoE-/- and ApoE-/-/AMPK alpha 2-/- mice maintained on this diet." (PMID 21980456, 2011).
aortic atherosclerosis (continued). "Interestingly, our previous study also showed that chronic unpredictable mild stress (CUMS) promoted the development of aortic atherosclerosis in apoE-/- mice, which may be related to activation of TLR4 and NF-κB in the aorta." (PMID 25860573, 2015). "More recently, a third study of apoE-/- mice fed a high fat diet and exposed to PM2.5 in the same facility confirmed the enhancement of aortic atherosclerosis as assessed by the percentage of the plaque area in the aortic arch by ultrasound bio-microscopy." (PMID 19761620, 2009). "Consistently, hyperlipidemic rabbits exposed to PM10 (particulate matter ≤ 10 μm in aerodynamic diameter) or ApoE−/− mice exposed to PM2.5 (≤ 2.5 μm ) develop advanced coronary and/or aortic atherosclerosis." (PMID 17431486, 2007). "Our findings revealed that absence of apoE in rabbits resulted in a significant increase in aortic atherosclerosis." (PMID 39087075, 2024). "In ApoE–/– mice, immunization with P210-PAMs dampened P210-specific CD4+ T cell proliferative response and CD8+ T cell cytolytic response, modulated macrophage phenotype, and significantly reduced aortic atherosclerosis." (PMID 35536648, 2022). "In a genetic model of hyperhomocysteinemia, CBS-/-ApoE-/- mice exhibited accelerated aortic atherosclerosis compared with ApoE-/- mice after 6 months of age in the absence of dietary manipulation." (PMID 29018349, 2017). "For example, the VSMC-specific deficiency of Runx2, a positive regulator of osteoblast differentiation, reduces calcification of atherosclerotic plaques in dyslipidemic apoE knockout mice, but fails to halt progression of aortic atherosclerosis in this model." (PMID 29023576, 2017). "In an apolipoprotein E-deficient animal model, overexpression of human HSP27 resulted in a 35% reduction in aortic atherosclerosis in female, but not male, mice." (PMID 23304456, 2012).
Hyperglycemia (87 papers, 2010 to 2025). An increased concentration of glucose in the blood. "To investigate the mechanisms underlying hyperglycemia‐induced vascular injury, we conducted a 4D‐label‐free quantitative proteomic analysis of whole aortas from three groups of diabetic ApoE−/− mice: HG 0 W, HG 6 W, and HG 20W." (PMID 40135829, 2025). "We induced hyperglycemia in ApoE-deficient (ApoE−/−) mice by intraperitoneal injection of streptozocin (STZ; 50 mg/Kg) for 5 days and accelerated diabetic atherosclerotic disease through a high fat diet (HFD)." (PMID 40421131, 2025). "The double mutant mice exhibited hyperglycemia on control chow compared to WT mice, mice with elastin insufficiency alone, or mice with ApoE deficiency alone." (PMID 26167199, 2014). "The present study demonstrated that dietary supplementation of PA significantly improved hyperglycemia and renal function in apolipoprotein E-deficient mice." (PMID 24023581, 2013). "To determine the effect of hypercoagulability on hyperglycemia-associated atherosclerotic plaque development, we directly compared diabetic ApoE-/- mice expressing wild-type thrombomodulin (TM, Thbd) with diabetic ApoE-/- mice expressing the TMPro mutant (TMPro/Pro mice)." (PMID 35631132, 2022). "However, elastin insufficiency coupled with ApoE deficiency (Eln+/−;ApoE−/−) was associated with hyperglycemia." (PMID 26167199, 2014). "Elevated levels of HDL-bound apoE in T2DM are shown to positively associate with its production rates as well as HbA1c levels, suggesting a potential role of hyperglycemia in the regulation of HDL-bound apoE kinetics." (PMID 38994965, 2024). "This study aimed to investigate the effects of CTRP9 on hyperglycemia-induced endothelial cell senescence and atherosclerotic plaque formation in diabetic apolipoprotein E knockout (ApoE KO) mice." (PMID 34744738, 2021). "Studies of hyperglycemia’s effect on vascular lesions in the apoE-/- mouse model revealed that advanced lesions appear in hyperglycemic mice earlier than they do in normoglycemic controls." (PMID 32155866, 2020). "To explore the effects of hyperglycemia in advanced and fibrous carotid atherosclerotic plaques, induced by a shear stress modifier, we used ApoE−/− GK+/− mice with ApoE−/− mice as controls." (PMID 29760458, 2018). "Hyperglycemia also increases ROS production and oxidation of the ApoE protein in astrocytes, preventing ApoE-mediated proteolysis of Aβ." (PMID 29706884, 2018). "While the body weights of wild type C57BL/6J, untreated and NA/STZ-treated ApoE KO mice were similar, luseogliflozin treatment significantly suppressed weight gain in NA/STZ-treated ApoE KO mice with the normalization of hyperglycemia." (PMID 28777298, 2017). "In the same line of evidence, we have not observed any differences in body weight, lipid profile or hyperglycemia between both Tnfsf12+/+ApoE−/− and Tnfsf12−/−ApoE−/− mice." (PMID 28447667, 2017). "In our present study, we show that UDCA blocks hyperglycemia-induced ER stress and the downstream inflammatory response thereto in both ECs and aortic tissues of diabetic ApoE-/- mice." (PMID 26807573, 2016). "First, UDCA suppressed the inflammatory response caused by hyperglycemia; UCDA blocked ER stress and the downstream signaling pathway thereof in ECs and ApoE-/- mice." (PMID 26807573, 2016). "We conclude that, compared to normoglycemic ApoE−/− mice, the GK+/−ApoE−/− mice showed a stable and reproducible hyperglycemia, which induced accelerated atherosclerotic lesion progression as well as impaired lesion regression after lipid lowering." (PMID 27774459, 2016). "The high HDL level should contribute, at least partially, to the resistance of BALB.apoE-/- mice to diet-induced hyperglycemia." (PMID 22204493, 2011). "Recently, we have found that apoE-/- mice on the C57BL/6 (B6) genetic background develop significant hyperglycemia when fed a Western-type diet." (PMID 22204493, 2011).
Hyperglycemia (continued). "To further investigate how hyperglycemia affects atherosclerotic plaque progression in the ApoE−/− GK+/− mice we analyzed the macrophage and T-cell contents in plaques by immunohistochemistry, as well as measured the levels of monocytes and Tregs in blood by flow cytometry." (PMID 29760458, 2018). "Thus, ApoE−/− GK+/− mice are appropriate as a model to study the effect of hyperglycemia per se on arterial repair and atherosclerotic plaque formation." (PMID 29760458, 2018). "Notably, while STZ-induced hyperglycemia augmented cell proliferation marker PCNA expression in ApoE−/− mice (3.6-fold vs. Control), CrP administration significantly inhibited PCNA expression (80% vs. STZ)." (PMID 28345659, 2017). "Its insulinotropic and antidiabetic effects were also observed in the HFHS diet-treated ApoE−/− mice, suggesting that CE should could potentially treat hyperglycemia." (PMID 28091547, 2017). "Morphometric quantification of aortic root lesions revealed that CrP prevents plaque development in hyperglycemic ApoE−/− mice, depicted by the profound decrease in hyperglycemia-induced proliferative smooth muscle cell abundance as well as macrophage and leukocyte infiltration." (PMID 28345659, 2017). "However, Eln+/−; ApoE−/− double mutant mice exhibit notable hyperglycemia, adipocyte hypertrophy, inflammation of adipose tissue, and ectopic lipid accumulation in liver tissue." (PMID 26167199, 2014). "STZ-induced hyperglycemia increased α-SMA (1.6-fold) and PCNA staining (2.0-fold) in ApoE−/− mice, indicating enhanced smooth muscle cell content and cell proliferation." (PMID 28345659, 2017). "Consistent with our previous study, oral administration of hidrosmin in diabetic ApoE KO mice did not affect hyperglycemia but partially reduced serum levels of total cholesterol and triglycerides." (PMID 36552707, 2022). "STZ induced sustained hyperglycemia in ApoE (−/−) mice, while injection of any AAVs did not alter fasting blood glucose or beta-cell mass at analysis." (PMID 35935990, 2022). "Taken together, the results from our study indicate that hyperglycemia per se does not accelerate inflammatory processes in the ApoE−/− GK+/− mouse." (PMID 29760458, 2018). "In the atheroprogression and atheroregression studies, hyperglycemia was very stable and more profound in GK+/−ApoE−/− mice compared to ApoE mice (data not presented)." (PMID 27774459, 2016). "In this report, TRAIL-/-ApoE-/- mice had significantly elevated weight gain and hyperglycaemia at 8 w, and surprisingly, these parameters were not sustained by 20 w." (PMID 24667560, 2014). "Two factors can explain this difference: on the one hand, the nondiabetic ApoE-/- mice may not have a significant vascular inflammatory response induced by hyperglycemia." (PMID 33436015, 2021). "Furthermore, the absence of diabetes-induced increase in lipid levels in the ApoE−/− GK+/− mouse makes it an appropriate model to isolate the effects of hyperglycemia on atherosclerotic plaque development." (PMID 29760458, 2018). "Interestingly, lesion formation remained unaffected by CrP in ApoE−/− control mice that were not subjected to STZ-induced hyperglycemia." (PMID 28345659, 2017). "Consequently, they had significantly lower levels of TC, LDL-C, HDL-C, and PON1 activity, and higher TG and apoE levels, regardless of the presence of hyperglycemia." (PMID 27519051, 2016). "Similar to STZ-treated ApoE−/−, TSP-1−/−/ApoE−/− dKO mice developed significant hyperglycemia upon STZ treatment achieving non-fasted blood glucose levels ≥ 250 mg/dl." (PMID 28345659, 2017).